LINC00482 (long independently transcribed non-coding RNA 482)
Synonyms: FLJ39421; formerly C17orf55
Gene: Long non-coding RNA gene on chromosome 17 (81,303,771 to 81,311,237, reverse strand). Ensembl gene ENSG00000185168.
Diseases named in the same sentence as LINC00482 in open-access papers:
LINC00482 is named in the same sentence as 4 diseases in open-access papers, as found by Europe PMC text mining. Sharing a sentence is not in itself a finding about the gene and the disease. The quoted sentences say what the papers report.
bladder cancer (3 papers, 2020 to 2023). "In conclusion, our research highlighted the potential of LINC00482 as a novel therapeutic target for bladder cancer treatment." (PMID 33323547, 2020). "Similarly, decreased LINC00482 in the present study also suppressed inflammation in bladder cancer by inhibiting the secretion of pro-inflammatory factors." (PMID 33323547, 2020). "LINC00482 promotes MMP15 expression by recruiting FOXA1, leading to the inhibition of inflammation and angiogenesis in bladder cancer, consistent with our results." (PMID 36879212, 2023). "A comprehensive analysis of bladder cancer microarray data GSE61615 revealed 4 significant differential LincRNAs, LINC00051, LINC00116, LINC00338 and LINC00482, where logFC of LINC00482 was the highest." (PMID 33323547, 2020).
pancreatic cancer (1 paper, 2020). "For example, LINC00482 and C17orf89 were not correlated in either FANTOM5 or TCGA pancreatic cancer, but they became co-expressed in response to Wnt inhibition." (PMID 33092630, 2020).
LINC00482 also shares sentences with these, for which no sentence is quoted: tumor (2 papers); cancer (1).